CNOT1 (CCR4-NOT transcription complex subunit 1)
Diseases named in the same sentence as CNOT1 in open-access papers (continued):
Sharing a sentence is not in itself a finding about the gene and the disease.
lipodystrophy (1 paper, 2019). A congenital or acquired disorder characterized by abnormal loss or redistribution of the adipose tissue in the body. "Metabolic alterations, together with decreased adipocyte masses, indicate that adipose tissue-specific suppression of CNOT1 results in lipodystrophy-like phenotypes." (PMID 31652943, 2019). "Further analyses are required to determine whether the antagonism between adipose tissue and muscle differentiation is responsible for the appearance of this fibrous material in the adipose tissues lacking CNOT1 and for muscular hypertrophy in lipodystrophy." (PMID 31652943, 2019). "Here, we show that mice lacking the Cnot1 gene (Cnot1-AKO mice) have reduced WAT and BAT masses, together with symptoms of lipodystrophy and cold sensitivity." (PMID 31652943, 2019).
melanoma (1 paper, 2023). A malignant, usually aggressive tumor composed of atypical, neoplastic melanocytes. "However, SNPs in the CNOT1 gene have been reported in B-cell paediatric ALL and missense mutations have been frequently reported (376 out of 481 total mutations) in colorectal, melanoma, uterine and many other cancers (cbioportal project)." (PMID 37508532, 2023).
Neurodevelopmental delay (1 paper, 2024). "Head circumference in cases of CNOT1 mutation was only reported once and was severely reduced, i.e. at 0.5th centile, suggesting smaller brain volume with the risk for neurodevelopmental delay." (PMID 38180040, 2024).
non-small cell lung carcinoma (1 paper, 2024). A group of at least three distinct histological types of lung cancer, including non-small cell squamous cell carcinoma, adenocarcinoma, and large cell carcinoma. "The leading genes contributing towards a higher targeting of RNA degradation among males include CNOT1, CNOT2, CNOT3 and DCP1A, all of which have previously been found to have prognostic significance in various cancers, including non-small cell lung cancer." (PMID 39107837, 2024).
prostate carcinoma (1 paper, 2017). A carcinoma that arises from epithelial cells of the prostate gland. "CNOT1 was mutated in all MSI prostate cancer cell lines but this was, in all cases, an heterozygous mutation and occurred closed to the end of the coding region." (PMID 27907910, 2017).
thyroid (1 paper, 2016). "SPOP, NF1, BRIP, CNOT1, KMT2C and STAG2 mutations previously identified in PTC might be involved in thyroid tumorigenesis in a type-nonspecific manner." (PMID 27626165, 2016).
cancer (9 papers, 2016 to 2024). A tumor composed of atypical neoplastic, often pleomorphic cells that invade other tissues. "Also here we identified CNOT1, DAB2IP and PRRT2 as novel MSI target genes, in the MMR-deficient cancer cell lines, although with varying frequency." (PMID 27907910, 2017). "The two genes CNOT1 and CNOT3 were also identified to be involved in a type 2 sub-network, and be enriched in RNA degradation (pathway ID 03018), where CNOT3 is a NCG cancer gene." (PMID 28415609, 2017). "In addition, BPTF, SIN3A, CNOT1 and YY1 were highly positively correlated in both pan-cancer and ccRCC datasets." (PMID 33232269, 2020).
tumor (9 papers, 2016 to 2022). "We predict that BPTF, SIN3A and CNOT1 enhance genomic stability and inhibit tumor cell formation by positively regulating ubiquitination in ccRCC." (PMID 33232269, 2020). "Restoration of the protein expression of LMNA rescued tumor cell growth, showing that the control of cell proliferation by CNOT1 was largely dependent on LMNA." (PMID 28188704, 2017). "The tumor growth curve demonstrated that knockdown of CNOT1 significantly inhibited tumor growth in vivo." (PMID 28188704, 2017). "Collectively, our data support a model of CNOT7, TOB1, CNOT1, and RNA-binding proteins collectively exerting post-transcriptional control on a metastasis suppressive transcriptional program to drive tumor cell metastasis." (PMID 26807845, 2016). "Likewise, irradiation induced cNot1 deadenylase activity in several tumor cell lines, e.g., FaDu, SAS, and PC3 cells, and in normal fibroblasts." (PMID 29253018, 2017). "Overexpression of LMNA could rescue CNOT1 knockdown‐mediated tumor inhibition and Hedgehog signaling pathway inhibition." (PMID 28188704, 2017). "The tumor volume and weight were smaller in the CNOT1‐knockdown group than in the scramble group." (PMID 28188704, 2017). "The results showed that CNOT1 knockdown could also dramatically impede tumor growth potential in vivo." (PMID 28188704, 2017). "Intriguingly, these tumor-specific gene fusion events contain one TF of SSX2 and seven oncogenes of SS18, SSX1, SSX2, BCOR, CNOT1, HIST2H2AC, and TOP1." (PMID 36118864, 2022). "Then the expressions of CNOT1 and LMNA in the tumor tissues of tumor‐bearing mice were detected by IHC analysis." (PMID 28188704, 2017).
infection (3 papers, 2018 to 2025). The state of being infected such as from the introduction of a foreign agent such as serum, vaccine, antigenic substance or organism. "The loss of Tab182 and CNOT1 favors the enhanced expression of AdE1A and AdE1B55K proteins in the early stages of infection." (PMID 29593045, 2018). "Greater abundance of scaffold protein CNOT1 and nucleases are likely to increase the functional availability of the entire complex during infection." (PMID 37846490, 2023). "A time course of infection demonstrated impaired accumulation of UL44 in CNOT1‐depleted cells compared to control cells from 48 HPI." (PMID 37846490, 2023). "Depletion of CNOT1 led to an 85 and 72% reduction in infection with siRNAs #1 and #2, respectively, while CNOT3 targeting led to reductions of 92 and 80%." (PMID 37846490, 2023). "By contrast, infection with clinical HCMV strain TB40/E was acutely sensitive to CNOT1 and CNOT3 depletion, displaying reduced accumulation of proteins representing each viral temporal gene class in knockdown cells." (PMID 37846490, 2023). "We thus compared host transcripts that gained 20 nt or more in poly(A)‐tail length and are consequently likely to experience a functional benefit, following infection (53%, 160/306 transcripts) with CNOT1 depletion (61%, 379/621 transcripts)." (PMID 37846490, 2023). "DRS permits identification of the specific mRNAs whose poly(A)‐tails are most affected by infection and CNOT1 disruption, albeit within the constraints of read depth limitations and bias toward abundant transcripts imposed on both sample sets." (PMID 37846490, 2023). "More viral DNA can be seen in the Tab182-depleted cells than in the control cells after both Ad5 and Ad12 infection; similarly, there is an even greater increase after CNOT1 depletion, consistent with increased AdE1A expression." (PMID 29593045, 2018). "Following infection of HeLa cells with either Ad5 or Ad12, levels of CNOT1, CNOT3, CNOT4, and CNOT7 were monitored by Western blotting." (PMID 29593045, 2018). "In a further study, it was shown that the concentration of viral DNA is increased in Tab182- and CNOT1-depleted cells 24 h after both Ad5 and Ad12 infection." (PMID 29593045, 2018). "This revealed a high proportion of overlap (91 transcripts; Fig EV5A), indicating that CNOT1‐responsive transcripts are among those whose poly(A) status is changed in infection, consistent with the possibility that altered CNOT1 targeting and/or activity occurs." (PMID 37846490, 2023). "In addition, the depletion of Tab182 and CNOT1 results in a limited increase in the viral DNA level during infection." (PMID 29593045, 2018). "However, in a further set of experiments, it was shown that when CNOT1 was depleted before infection with Ad5, there were notable increases in E1A and E1B55K expression levels compared to the controls." (PMID 29593045, 2018). "Depletion of Tab182 and CNOT1 favors the production of viral DNA during infection." (PMID 29593045, 2018). "Interestingly, mRNA levels for CNOT1, 2, and 3 increased by a maximum of twofold compared to uninfected cells during infections, suggestive of a translational modality to CNOT1 and CNOT3 protein upregulation, a feature previously reported for the regulation of CNOT3 expression in response to diet." (PMID 37846490, 2023). "CNOT1 and CNOT3 proteins dramatically increased during infections with both virus strains beginning at 24 HPI." (PMID 37846490, 2023). "At 72 h post infection (HPI), late in the virus lifecycle, accumulation of representative proteins from each temporal gene class was impaired when CNOT1 or CNOT3 were targeted by either of two independent siRNAs." (PMID 37846490, 2023). "To decipher how CNOT1 and CNOT3 promote viral replication, we examined the abundance of viral proteins and transcripts in a synchronous high MOI (multiplicity of infection) infection." (PMID 37846490, 2023).
infection (continued). "It is notable that in Tab182- and CNOT1-depleted cells, there is only a very limited induction of CDC25A after infection, whereas this is appreciable in control infected cells." (PMID 29593045, 2018). "In contrast to Tab182, the levels of CNOT1 and CNOT4 remained stable throughout the time course of infection." (PMID 29593045, 2018). "CNOT1 or CNOT3 depletion did not measurably impact the accumulation of VACV proteins, detected using a pan‐VACV antibody, or the accumulation of IE, early and late HSV‐1 proteins ICP4, US3, or gC following a low multiplicity infection." (PMID 37846490, 2023).
heart disease (1 paper, 2020). "The combined use of GWAS studies and cardiac model systems in this study has enabled us to connect CNOT1, CNOT7 and, overall, CCR4-NOT complex function to cellular and whole-heart phenotypes in the context of human heart disease." (PMID 32471864, 2020).
metabolic disorders (1 paper, 2025). "For instance, CNOT1, a component of the CCR4-NOT complex, is known to regulate mRNA stability and translation, processes that could be dysregulated in metabolic disorders." (PMID 40740938, 2025).
CNOT1 also shares sentences with these, for which no sentence is quoted: adenoma (2 papers); colon adenoma (2); gastric cancer (2); brain tumor (1); cyst (1); deafness (1); dilated cardiomyopathy (1); hepatitis C virus infection (1); hepatocellular carcinoma (1); Hyperglycemia (1); hypothyroidism (1); immune dysfunction (1); Insulin resistance (1); kidney disease (1); lymphoma (1); malaria (1); Parkinson disease (1); steatosis (1); triple-negative breast carcinoma (1).